KL (klotho)
Diseases named in the same sentence as KL in open-access papers (continued):
Sharing a sentence is not in itself a finding about the gene and the disease.
Obesity (40 papers, 2016 to 2026). Accumulation of substantial excess body fat. "Conversely, the knockout of Klotho in Lep (ob/ob) mice, characterized by leptin deficiency, has been shown to lead to a reduction in obesity and an increase in insulin sensitivity, ultimately resulting in diminished blood sugar levels." (PMID 38907289, 2024). "The purpose of this secondary analysis was to investigate the potential association between obesity, weight loss, and Klotho concentration." (PMID 37457921, 2023). "Obesity is associated with many chronic conditions and promotion of advanced aging activity, with Klotho being a biomarker of premature aging processes." (PMID 37457921, 2023). "In the studied pediatric group, increased serum Klotho concentrations were associated with obesity and IR." (PMID 32546231, 2020). "This study clearly shows for first time that obesity of Zucker rats is associated to increased urinary glutamyl and alanyl aminopeptidasic activities and to increased urinary excretion of Klotho, changes that were detected as early as 2 months old." (PMID 30483154, 2018). "These associations suggest that Klotho-related alterations may reflect biological processes linked to inflammation and muscle dysfunction in obesity." (PMID 41752116, 2026). "The potential mechanisms underlying the association between metabolically healthy phenotypes and Klotho are not yet fully understood, but they may be related to chronic inflammation caused by obesity or metabolic disorders." (PMID 40060377, 2025). "Numerous studies have robustly linked klotho levels to obesity." (PMID 40076542, 2025). "A large-scale population-based study further indicated that obesity is associated with decreased Klotho levels, with significant differences in Klotho concentrations observed in adults who underwent weight loss interventions, correlating with the extent of weight loss achieved." (PMID 40060377, 2025). "Therefore, we can surmise that obesity is a state of Klotho deficiency, which becomes much more pronounced when obese animals are submitted to IRI." (PMID 38684767, 2024). "Recent studies have also demonstrated that obesity is associated with reduced expression of Klotho." (PMID 37528365, 2023). "This may suggest that treatment of overweight and obesity through weight loss may increase Klotho concentration, potentially counteracting the accelerated aging effects of obesity." (PMID 37457921, 2023). "Obesity among women was significantly and inversely associated with serum klotho levels." (PMID 36061981, 2022). "Circulating klotho levels were negatively associated with being overweight (beta coefficient: − 22.609, p = 0.0025), obesity (beta coefficient: − 23.716, p = 0.0011), current smoking (beta coefficient: − 46.412, p < 0.0001), and alcohol consumption (beta coefficient: − 51.194, p < 0.0001)." (PMID 36221064, 2022). "In addition, the knock-out of the Klotho gene in leptin-deficient mice reduces obesity and increases insulin sensitivity." (PMID 35053218, 2022). "These physiological consequences, in turn, may lead to reduced S-Klotho levels, as it is known that factors such as obesity, vitamin D deficiency, and systemic inflammation suppress renal klotho synthesis." (PMID 32806634, 2020). "Measurements of GluAp, AlaAp, and Klotho may represent a novel, specific and non-invasive diagnostic approach to assess kidney fibrosis and may have a potential use not only in diagnosis but also in prognosis of obesity-associated renal lesions." (PMID 30483154, 2018). "Although fibroblast growth factor 21 (FGF21) and its co‐receptor, Klotho, are implicated in mediating DPR benefits, diet‐induced obesity by HF appears to blunt their response." (PMID 41549510, 2026). "Recent studies have confirmed that Klotho knockout mice are resistant to obesity induced by a high-fat diet due to a reduction in white adipose tissue, implying an effect of Klotho on adipocyte differentiation and maturation in vivo." (PMID 40007807, 2025).
Obesity (continued). "The review uncovered a complex relationship between klotho protein levels and various aspects of obesity and related health issues." (PMID 40076542, 2025). "Klotho is an anti-aging protein, and obesity and inflammation have been identified as having a relationship with Klotho." (PMID 40375945, 2025). "In general, obesity is often accompanied by increased levels of inflammation in the body, which can damage cells and tissues, and affect the synthesis and secretion of Klotho." (PMID 40060377, 2025). "Soluble Klotho levels are also lower in individuals with obesity, particularly in women and in girls with early-onset weight gain, showing sex-specific patterns." (PMID 41303567, 2025). "Lower concentrations of s-klotho have been found in obese women compared to those with normal weight, suggesting potential gender disparities in klotho expression related to obesity." (PMID 40076542, 2025). "In diet-induced obesity (DIO) mice, Klotho administration reduces adipose tissue and hepatic lipid buildup, mainly decreasing obesity by blocking acetyl-CoA carboxylase (ACC), which increases fat oxidation." (PMID 40119098, 2025). "In mouse models of obesity, selective clearance of senescent cells using the senolytics dastatinib and quercetin restored klotho levels within the kidney, highlighting an inverse relationship between klotho and cellular senescence." (PMID 38995865, 2025). "The biological functions attributed to Klotho can give rise to various physiological effects, as well as diseases, including obesity." (PMID 40007807, 2025). "In the simple mediation model, significant indirect effects were observed for general obesity (9.19%), NAFLD (4.19%), and CKD (20.42%), indicating that CKD accounted for the largest proportion of Klotho’s protective association with CVD." (PMID 40369033, 2025). "This suggests a potential direct involvement between Klotho expression level and obesity/aging relationships." (PMID 40007807, 2025). "Previous studies have investigated the relationship between obesity and IGF-1 levels and found a dysregulation of IGF-1 pathways in individuals with obesity, suggesting a potential link between body fat and Klotho." (PMID 40060377, 2025). "Among the six studies that established a relationship between klotho levels and obesity, three were related to MS, three were related to cardiovascular risk, four were related to physical exercise and diet, and four were related to older adult patients." (PMID 40076542, 2025). "Recent evidence has shown Klotho to be lower in adults with obesity compared to their normal-weight counterparts." (PMID 40060377, 2025). "Klotho-overexpressing mice exhibit increased insulin sensitivity and resistance to diet-induced obesity." (PMID 38501099, 2024). "For instance, a study observed a reduction in plasma Klotho levels among individuals with type 2 diabetes and obesity." (PMID 38907289, 2024). "Baseline Klotho concentration for the middle-aged adults with overweight or obesity included in this secondary analysis was approximately 930 pg/mL." (PMID 37457921, 2023). "Treatment with FGF-21 resulted in weight loss and restored the decreased expression of Klotho induced by the high-fat diet, indicating the crucial role of FGF-21 in regulating Klotho expression during obesity development." (PMID 37528365, 2023). "Evidence has shown Klotho to be lower in adults with obesity compared to their normal-weight counterparts." (PMID 37457921, 2023). "In contrast, young Japanese women with restrictive-type anorexia nervosa or obesity had significantly lower serum klotho levels than those with a healthy body weight." (PMID 36061981, 2022). "In our study, we noted that children and adolescents affected by obesity showed higher serum Klotho concentrations than those with normal body weight." (PMID 32546231, 2020).
Obesity (continued). "The aim of this study was to investigate if urinary glutamyl aminopeptidase (GluAp), alanyl aminopeptidase (AlaAp), Klotho and hydroxyproline can be considered as potential biomarkers of renal injury and fibrosis in an experimental model of obesity." (PMID 30483154, 2018). "Klotho knockout rats are resistant to obesity even when exposed to a high fat diet 53,54, revealing a clear synergy between the soluble marker and diet." (PMID 28076518, 2016). "Eliminating KL function from mice results in the generation of lean mice with almost no detectable fat tissue, and induces a resistance to high-fat-diet-stimulated obesity." (PMID 27478698, 2016). "Studies suggest a negative association between circulating soluble Klotho levels and obesity, particularly among women." (PMID 41303567, 2025). "Therefore, obesity and metabolic disorders affect the relationship between metabolically healthy phenotypes and Klotho through mechanisms such as inducing chronic inflammation, interfering with insulin function and abnormal secretion of adipokines." (PMID 40060377, 2025). "Klotho has been reported to counteract insulin resistance and improve lipid metabolism, and lower Klotho levels in obesity may represent a feedback response to persistent metabolic stress." (PMID 40678338, 2025). "A study revealed that cerebrospinal fluid levels of Klotho were significantly negatively correlated with body weight/BMI due to the central involvement in obesity’s pathological process, while soluble Klotho concentration was inversely correlated with abdominal obesity/high triglycerides." (PMID 40007807, 2025). "This underscores the significant role that klotho could have in maintaining metabolic health, particularly regarding its relationship with conditions such as obesity, lipid imbalances, and elevated blood sugar levels." (PMID 40076542, 2025). "While we hypothesize that metabolically unhealthy obesity may affect Klotho levels through low-grade inflammation or oxidative stress, the cross-sectional design still leaves room for reverse causality." (PMID 40060377, 2025). "Klotho is a potential biomarker for obesity, MS, and sarcopenic obesity." (PMID 40076542, 2025). "The relationship between Klotho and conditions such as obesity remains incompletely understood." (PMID 41303567, 2025). "Notably, women who developed obesity early in life exhibited significantly lower soluble Klotho levels compared to their normal-weight counterparts." (PMID 41303567, 2025). "The findings reveal a significant negative association between WWI and serum Klotho concentrations, suggesting that WWI may serve as a predictive indicator of serum Klotho levels, with implications for understanding obesity's influence on aging." (PMID 40678338, 2025). "Role of Hormonal and Genetic Mediators: The FGF23‐Klotho axis, influenced by mineral metabolism (notably phosphate and vitamin D), may be perturbed in obesity." (PMID 40678338, 2025). "High Klotho levels have been reported in adolescents with obesity." (PMID 37522130, 2023). "Potentially signifying Klotho concentrations may serve as a predictor for prediabetes, type 2 diabetes, cardiovascular disease, and obesity, however more work needs to be done in this area of research." (PMID 37457921, 2023). "Klotho expression levels may potentially be involved in the relationship between adiposity obesity and aging." (PMID 36814582, 2023). "These two studies prove the correlation between obesity and klotho protein from different angles." (PMID 36814582, 2023). "Despite controversy, this suggests that klotho may exert its anti-diabetic and anti-obesity effects through multiple pathways." (PMID 37143722, 2023). "One biomarker, among others, that may provide insight into the accelerated aging process and accompany obesity is Klotho." (PMID 37457921, 2023).
Obesity (continued). "In a 16-week exercise training program among individuals with obesity, participants showed a substantial increase in Klotho concentration in response to an acute exercise bout performed post-intervention compared to an acute exercise bout performed pre-intervention." (PMID 37457921, 2023). "Therefore, this study aimed to examine the association between serum klotho levels and well-established risk factors for CVD, including smoking, alcohol consumption, obesity, cholesterol levels, physical inactivity, and chronic diseases." (PMID 36221064, 2022). "Interestingly, the Klotho level appeared to be decreased even more among individuals with normal weight compared with those with overweight and obesity." (PMID 35761232, 2022). "Therefore, the increase in Klotho levels accompanied by a decrease in FGF23 induced by AT seems to be an important therapeutic target for renal damage attenuation inherent to obesity conditions." (PMID 34621463, 2021). "Additionally, obesity can lead to increased visceral fat, which secretes adipokines (such as adiponectin) that may negatively affect Klotho level." (PMID 40060377, 2025). "Thus, early-life obesity may induce long-lasting biological alterations affecting Klotho expression, potentially with sex-specific implications." (PMID 41303567, 2025). "Experimental studies have shown that Klotho-deficient mice exhibit widespread tissue atrophy, particularly in the liver and adipose tissue and reduced insulin secretion, despite the absence of obesity." (PMID 41303567, 2025). "We hypothesized that obesity would aggravate renal IRI in a Klotho/ROS-dependent pathway in mice." (PMID 38684767, 2024). "Consequently, individuals with overweight/obesity may have a greater dependence on a higher intake of dietary fiber to facilitate the production of Klotho protein." (PMID 37513564, 2023). "The study sample included individuals with overweight or obesity but otherwise relatively healthy individuals, therefore functional impairments needed to observe associations with Klotho concentrations may not have been detected." (PMID 37457921, 2023). "In addition, reduced levels of klotho in white adipose tissue were found to be associated with high fat-induced obesity in non-human primates." (PMID 36814582, 2023). "However, the influence of intentional weight loss on Klotho concentration among adults with overweight or obesity has not been well characterized." (PMID 37457921, 2023). "Whether the obesity history is associated with lower klotho levels has not been previously explored." (PMID 36061981, 2022). "Finally, mice that lack the Klotho gene are resistant to obesity induced by a high-fat diet." (PMID 32546231, 2020). "Considering that obesity may lead to a reduced metabolic rate and is associated with an increased risk of multiple chronic diseases, thereby promoting aging and shortened life expectancy, it seems particularly important to investigate the association between ABSI index and Klotho protein." (PMID 40007807, 2025). "Among metabolically healthy versus metabolically unhealthy individuals, normal-weight individuals (MH-NW and MU-NW) tended to have higher Klotho levels, while individuals with obesity (MHO and MUO) had lower serum Klotho levels." (PMID 40060377, 2025). "This study investigates the relationship between the weight‐adjusted waist index (WWI) and serum Klotho levels in adolescents, highlighting WWI as a potentially more accurate obesity indicator than traditional measures like BMI." (PMID 40678338, 2025). "It is typically only when severe metabolic abnormalities occur, such as being metabolically unhealthy and obesity (e.g., MUO), that a significant decrease in Klotho levels is observed." (PMID 40060377, 2025).
Obesity (continued). "However, when adults with overweight or obesity undergo a behavioral weight loss intervention using dietary restriction and two intervention groups including physical activity, the association between change in Klotho concentration and weight loss was not altered." (PMID 37457921, 2023). "After adjustment for potential confounders, women categorized as always obese or who developed obesity ten years before the baseline BMI had on average 40 and 63.1 pg/ml lower serum klotho levels compared with their never-obese counterparts, respectively." (PMID 36061981, 2022). "In contrast, serum klotho levels did not significantly differ in men, irrespective of their obesity history." (PMID 36061981, 2022). "Concerning children and adolescents, the literature does not provide sufficient data on the relationship between obesity and Klotho levels in these age groups." (PMID 32546231, 2020). "Mice that lacked Klotho activity are lean owing to the reduced white adipose tissue accumulation, and are resistant to obesity induced by a high-fat diet." (PMID 27478698, 2016). "Similarly, non-obese women at the age of 25 who developed obesity later in life had 55.5 pg/ml lower klotho levels than those that were never obese." (PMID 36061981, 2022).
renal failure (38 papers, 2012 to 2026). "Concomitantly, Klotho deficiency resulting from kidney failure worsens cardiac remodeling and function." (PMID 32188018, 2020). "We have previously shown that Memo cKO animals develop kidney failure at age 12–14 weeks or five weeks after recombination, and during advanced CKD, a severe loss of Klotho protein aggravates the inability of the kidney to excrete phosphate." (PMID 36434320, 2023). "Klotho is closely related to inflammatory responses and is a potential target for ameliorating kidney failure." (PMID 37261217, 2023). "Recently, increasing evidence has shown that Klotho levels are lower in patients and animal models with renal insufficiency, even though glomerular filtration rate (GFR) is only slightly decreased." (PMID 35509269, 2022). "Reduction in plasma levels of Klotho in middle-aged rats can be attributed to kidney tissue damage or kidney failure." (PMID 30524691, 2018). "Since Klotho is primarily expressed in the kidneys, renal insufficiency may significantly lower Klotho levels." (PMID 39723163, 2024). "This implies that during the inflammatory changes driven by folic acid overload, autocrine or paracrine FGF23 signaling via a canonical FGFR‐Klotho pathway may play only a minor role, in contrast to more chronic models of kidney failure driven by other pathophysiology." (PMID 36967231, 2023). "In our previous study with the peritoneal dialysis (PD) patients, we failed to confirm any significant associations between the amount of urinary excreted Klotho and that of albumin, which is the principal component of urinary protein in cases of glomerular proteinuria." (PMID 23176706, 2012). "In fact, since our patients had no renal insufficiency, and the kidney is the principal contributor of circulating Klotho 28, we assume that circulating Klotho levels are normal." (PMID 26538295, 2016). "While FGF23 is unlikely to exert its hormonal, Klotho-dependent effects on classical target organs in kidney failure, there is a possibility that FGF23 exerts nonclassical effects in a Klotho-independent manner." (PMID 36977891, 2023).